NKX2-1 (NK2 homeobox 1)
Diseases named in the same sentence as NKX2-1 in open-access papers (continued):
Sharing a sentence is not in itself a finding about the gene and the disease.
cancer (continued). "Together this indicated that co-occupancy of FOXA1 and NKX2–1 within “normal” AEC enhancers occurred approximately three times more often than within A549 cancer-specific enhancers." (PMID 34922464, 2021). "Further experiments showed that removing the gene for NKX2-1 made these cancer cells less responsive to drugs known as BRAF/MEK inhibitors that are commonly used to treat cancer." (PMID 33821796, 2021). "The seemingly dual activity of NKX2–1 in the MGE is similar to its double-edged characteristics in regulating cancer development and progression." (PMID 30217225, 2018). "Our study shows that the transcriptional silencing of ABI3 in cancer cells occurs via methylation and uncovered a previously unrecognized role for NKX2-1 in the regulation of ABI3." (PMID 27036019, 2016). "Takahashi's group pointed out NKX2-1 as a double-edged sword for cancer cell survival and progression." (PMID 25881545, 2015). "Overall, we provide novel insights into biological processes regulated by Nkx2-1 in different cell contexts in development, and cancer." (PMID 22242187, 2012). "Overrepresented pathway analysis performed by Ingenuity Pathway Analysis at E11.5 and E19.5 identified common Nkx2-1 targeted pathways at both stages, such as ‘mechanisms of cancer’ and ‘HGF signaling’." (PMID 22242187, 2012). "Staining of MUC1 (membrane), HIF1A (cytoplasm), and NKX2-1 (nucleus) classified cancer by subtype and cancer-free lung tissue with a failure rate of 11.0%." (PMID 23028920, 2012). "We concentrated our studies in Nkx2-1 proliferation-related target genes because of their link to development and cancer." (PMID 22242187, 2012). "NKX2-1 expression levels in various cancers were explored using TIMER." (PMID 38708353, 2024). "Targeting CXCLs/CXCR2 signaling may be a viable treatment strategy to suppress tumorigenesis and improve the survival outcome of LUAD patients with NKX2‐1‐low malignant tumors." (PMID 39113226, 2024). "In conclusion, we identified the homeodomain transcription factor NKX2–1 as a novel direct oncogenic inducer of serine/glycine synthesis enzymes in cancer, and we characterised downstream consequences on cellular nucleotide, redox and lipid metabolism and DNA methylation." (PMID 36932191, 2023). "To verify whether NKX2–1 is also driving serine/glycine synthesis in vivo, we performed targeted metabolite profiling of blood plasma from these mice at 11 weeks after cancer cell injection." (PMID 36932191, 2023). "As such, we hypothesised that NKX2–1 overexpression might also confer such a metastasis benefit to cancer cells." (PMID 36932191, 2023). "Genetic instability and the reprogramming of cancer cells may cause dedifferentiation and result in deregulation of TTF-1/NKX2-1." (PMID 36705380, 2023). "However, some turn off a gene that codes for a protein called NKX2-1, which leads to a type of cancer called invasive mucinous adenocarcinoma (or IMA for short)." (PMID 33821796, 2021). "Interestingly, we also detected that the NKX2-1 encoding TTF1, the most specific marker for cancers originating from the lung, was downregulated in SQ, in line with recent knowledge of SQ immunomarkers." (PMID 25325012, 2014). "Importantly, we show that PSPH is essential for the proliferation of NKX2–1 expressing cancer cells, and we uncover that NKX2–1 overexpressing cells are sensitised to metabolic drugs, including the dual SHMT1/2 inhibitor sertraline and the topoisomerase II inhibitor etoposide." (PMID 36932191, 2023). "Because NKX2–1 copy number gains also have been identified in LUAD and NEPC, we investigated whether NKX2–1 associated elevation of serine/glycine synthesis enzyme expression is uniformly observed across all cancer types." (PMID 36932191, 2023). "Therefore, we propose that NKX2–1 overexpression could represent a survival mechanism of cancer cells to manage oxidative stress during metastasis." (PMID 36932191, 2023).
cancer (continued). "Subsequently, the LUAD marker genes NAPSA, NKX2-1, the LUSC marker genes TP63, KRT5, as well as EPCAM and MET were adopted to identify the cancer cell clusters." (PMID 38382091, 2024). "We found that the cancer subtype markers (GRP, CHGB, NEUROD1, and CHGA for NET; KRT5, DSC3, KRT6B, TP63, and KRT6A for SCC; and NKX2-1, KRT7, NAPSA, and MUC1 for ADC) were specifically expressed in the corresponding cancer subtypes." (PMID 35962452, 2022). "Cancer cells were identified with canonical markers of LUAD and alveolar epithelial cells (e.g., SFTPB, SFTPC, EPCAM, NAPSA, and NKX2-1)." (PMID 35874770, 2022). "The LUAD maker NKX2-1 was reported to suppress LUAD progression, whereas RUNX2 was reported as key regulator to promote cancer progression." (PMID 34001209, 2021). "In contrast, A549 cancer-specific enhancers contained considerably fewer instances of FOXA1 and NKX2–1 peak co-occurrence (8.6%)." (PMID 34922464, 2021). "Through VENN analysis, we detected 603 upregulated and 1043 downregulated DEGs overlapping in the three cancer cell lines, including 16 upregulated TFs (e.g., HOXA2, HOXB2, HOXC10, and NKX2-1) and 36 downregulated TFs (e.g., BACH1 and CDX1), respectively." (PMID 32156290, 2020). "For example, ASCL1, CDX2, IRF4, MITF, NKX2-1, PAX8 and SOX2 were pinpointed as outliers in cell lines of their corresponding cancer tissue origins." (PMID 31050342, 2019). "Furthermore, the TFs from the inhibitor of differentiation (ID) family, such as ID1 and ID3, along with the homeobox TF NK2 homeobox 1 (NKX2-1), are capable of modulating the TIC phenotype in cancer cells." (PMID 40356596, 2025). "The concept of hybrid identity states and the discovery of the NKX2-1–HNF4α complex could also extend beyond LUAD and inform treatment strategies for other cancers affected by lineage plasticity." (PMID 40707360, 2025). "In summary, these results illustrate the dependence of NKX2–1 expressing cells on the serine/glycine synthesis pathway for nucleotide metabolism and highlight these processes as promising therapeutic targets in NKX2–1-driven cancers." (PMID 36932191, 2023). "Exercise-based approaches have recently been shown to impact the rno-miRNA-regulated target cancer gene candidates ITPR3, SOCS6, ITGA6, and NKX2-1 as biomarkers for cancer prognosis in rheumatoid arthritis diagnoses in pristane-induced arthritis (PIA) rat models." (PMID 36012617, 2022). "In cancer-specific enhancers in A549 cells, there was far less enrichment for both NKX2–1 and FOXA1, with no obvious differences in TF position relative to the center of the peak." (PMID 34922464, 2021). "This revealed that the NKX2-1 protein is needed to initiate the formation of cancer cells but is not required for the growth of already established BRAF-driven tumors." (PMID 33821796, 2021). "Indeed, almost 60% of cancer-specific A549 enhancers lacked any binding for FOXA1 or NKX2–1, suggesting that the colocalization of FOXA1 and NKX2–1 observed in A549 cells is primarily driven by enhancers preserved in normal tissues." (PMID 34922464, 2021). "Most slides from cancer-free tissue lacked expression of CCND1, CD44, CDH1, EGFR, ERBB2, KIT, keratins, NOTCH1, PAK1, PTGS2, SNAI1, and VIM but showed staining of MUC1, HIF1A, NKX2-1, SFTPC, and STAT3, which were also found in AdCa." (PMID 23028920, 2012).
adenocarcinoma (81 papers, 2003 to 2026). A common cancer characterized by the presence of malignant glandular cells. "It has been previously demonstrated in adenocarcinoma and in the adult distal lung, that loss of NKX2-1 leads to adoption of a gastric transcriptional phenotype." (PMID 32515350, 2020). "Amplification of the 14q13 locus containing the NKX2-1 gene is observed in only 11–15% of adenocarcinomas; DNA mutations in the open reading frame that may produce a mutated protein or truncations are rarely encountered." (PMID 22242187, 2012). "Both groups stained positive for NK2 homeobox 1 (NKX2.1), indicating that they were adenocarcinomas." (PMID 38195889, 2024). "As expected, club cell-originated KP tumors showed adenocarcinoma histology with positive expression of LUAD markers (NKX2-1 and SPC)." (PMID 38093367, 2023). "Further, we assessed potential amplification of the NKX2-1 gene, which encodes for TTF1, a biomarker that distinguishes adenocarcinomas." (PMID 37634047, 2023). "The staining of thyroid transcription factor 1 (TTF-1/NKX2–1) or napsin-A (NAPSA) can be used to support the diagnosis when the morphological feature of adenocarcinoma is unclear." (PMID 34187403, 2021). "Through pseudotime analysis and the expression level of Nkx2-1, we can infer that cluster 2 represents the initial adenocarcinoma cells, while clusters 0 and 1 are mucinous cells formed after Nkx2-1 knockout, and cluster 3 represents an intermediate state of LUAD transitioning towards IMA." (PMID 39584073, 2025). "The expression of the pluripotency genes OSKM, the adenocarcinoma marker NKX2-1, the lung surfactant proteins SFTP, the myofibroblast marker MYH and DNMT3A/3B was analyzed with qRT-PCR and the presence of the myofibroblast markers vimentin and α-SMA with immunofluorescence." (PMID 35081981, 2022). "NKX2-1 (also called TITF1 and TTF-1) encodes a homeobox transcription factor, and is found amplified at cytoband 14q13 in about 15% of NSCLCs (predominantly adenocarcinomas)." (PMID 26556242, 2015). "These links might be helpful in understanding the fact that patients with adenocarcinomas with higher levels of NKX2-1 expression have a better prognosis than those with lower or no expression of NKX2-1." (PMID 22242187, 2012). "NKX2–1 (another NEPC marker) also showed strong activity, while the adenocarcinoma lineage transcription factors AR and NKX 3.1 indicated far less inferred transcriptional activity." (PMID 41542660, 2026). "They observed pervasive transcriptional downregulation of adenocarcinoma lineage markers (NAPSA, NKX2-1, SFTA2, and SFTA3), validated orthogonally via multiplex immunohistochemistry." (PMID 41516316, 2025). "Both KP and KPU lesions following Ad5-SPC-Cre infections exhibited typical LUAD marker (NKX2-1 and SPC)-positive expression, with adenocarcinoma histology." (PMID 38093367, 2023). "Whether IMA exhibited NKX2‐1/TTF‐1 exon 1 expression was further validated using qPCR, revealing that 19 of 20 (95%) cases exhibited higher exon 1 expression relative to that of exon 4/5, compared to EGFR‐mutated adenocarcinoma that was immunohistochemically positive for TTF‐1." (PMID 34014042, 2021). "Conversely, NKX2-1 and mucins (MUC1, MUC5B) were more highly expressed in adenocarcinoma, as were ROS1 and CLDN3." (PMID 32381040, 2020). "Finally, the Adenocarcinoma factor shows association with the RNA expression of a number of keratins, negative coefficients for both copy number and RNA expression of SOX2 and positive association with both RNA expression and copy number of NKX2-1 (also known as TTF1)." (PMID 30379847, 2018). "In the current classification, a solid carcinoma without glandular structures or mucin production, but with immunohistochemical positivity for “adenocarcinoma markers”, i.e., TTF-1 (NKX2-1) and/or Napsin A, is diagnosed as an adenocarcinoma." (PMID 29538329, 2018).
adenocarcinoma (continued). "Several of the identified mGISTIC regions harbored known or putative adenocarcinoma driver candidates, such as EGFR, MDM2, KRAS, MYC, TERT, MET, CCND1, NKX2-1/TITF1, CDK4, ERBB2, ID1, RB1, CDKN2A and PTEN." (PMID 24205279, 2013). "The results of immunohistochemical assessments showed that Thyroid transcription factor 1 (TTF-1 or NKX2–1) and Cytokeratin 7 (CK7), which are sensitive and specific expressions (positive rate more than 70%) in NSCLC and especially in adenocarcinoma, were all significant positive." (PMID 25474437, 2014). "This phenomenon was rarely observed in tumors from other control groups, which predominantly produced intracellular mucin, suggesting that FoxA1 and FoxA2 likely have some specific functions in the regulation of the differentiation state of NKX2-1-negative adenocarcinoma." (PMID 30475207, 2018). "Although both components were NKX2-1-negative, markers of gastric differentiation were restricted to the adenocarcinoma component, and markers of squamous differentiation (including ΔNp63 and cytokeratins 5 and 14 (CK5 and CK14), but not SOX2) were selectively expressed in the SCC component." (PMID 30475207, 2018). "In particular, SWI/SNF interacts with the transcription factor NK2 homeobox 1 (NKX2.1/TTF-1) in CRPC-NE cells, but not in adenocarcinoma cells." (PMID 33144576, 2020).
neurological disorders (5 papers, 2015 to 2025). "This patient demonstrated lung, thyroid, and neurological disorders, similar to several reports on NKX2-1-related disorders." (PMID 32195974, 2020).
infection (4 papers, 2020 to 2023). The state of being infected such as from the introduction of a foreign agent such as serum, vaccine, antigenic substance or organism. "In KP and KPU tumors following Ad5-CC10-Cre infection, we classified subtypes of KP and KPU tumors by NKX2-1 and SOX2 expression levels." (PMID 38093367, 2023). "The analyses of non-thyroid cell viabilities, however, showed that AdNKX2-1 infection did not cause HepG2 liver cell death, which does not express PAX8 or NKX2-1." (PMID 34748583, 2021).
lung (3 papers, 2020 to 2025). "Previous reports have shown that gastric differentiation program was triggered in murine lung ADC following NKX2‐1 deletion, which involved the interaction of NKX2‐1 and FOXA1/FOXA2 to re‐program FOXA1/FOXA2 binding sites and preferential activation of certain target genes." (PMID 33439550, 2021).
endocrine diseases (1 paper, 2024). "List of included references for treatment and follow-up of endocrine diseases in patients with NKX2-1-RD." (PMID 39466809, 2024). "The primary challenge in managing NKX2-1-related disorders (NKX2-1-RD) is early diagnosis of the genetic defect and treating specific endocrine disorders." (PMID 39466809, 2024). "Through a complete analysis of the available evidence, this study presents a comprehensive overview of the current treatment and follow-up protocols for endocrine diseases in individuals with NKX2-1-RD for the first time." (PMID 39466809, 2024).
GI tumors (1 paper, 2021). "In our study, higher RUNX2 expression was detected in GII tumors compared to GI tumors, whereas NKX2-1 seemed to be specifically expressed in GI tumors." (PMID 34001209, 2021).
head and neck tumors (1 paper, 2022). "Except for JAK2 and NKX2-1, all genes were differentially expressed in primary head and neck tumors as compared to normal tissue." (PMID 35954343, 2022).
NKX2-1 also shares sentences with these, for which no sentence is quoted: small cell lung carcinoma (11 papers); small cell carcinoma (8); neuroendocrine tumor (7); Anxiety (6); Choreoathetosis (6); medullary thyroid carcinoma (5); neonatal respiratory distress syndrome (5); Intellectual disability (4); neuroendocrine carcinoma (4); renal cell carcinoma (4); breast tumor (3); gastric cancer (3); glioma (3); hepatocellular carcinoma (3); Hodgkins lymphoma (3); malignant mesothelioma (3); multinodular goiter (3); Myoclonus (3); respiratory disease (3); anaplastic thyroid carcinoma (2); autism (2); bronchopulmonary dysplasia (2); carcinoids (2); chronic obstructive pulmonary disease (2); colon cancer (2); cystic fibrosis (2); genetic disorders (2); Hirschsprung disease (2); large cell neuroendocrine carcinoma (2); lymph node metastasis (2).
A further 118 diseases each share a sentence with NKX2-1 in 2 papers or fewer.